MAPT (microtubule associated protein tau)
Diseases named in the same sentence as MAPT in open-access papers (continued):
Sharing a sentence is not in itself a finding about the gene and the disease.
cognitive decline (56 papers, 2012 to 2025). "Despite the fact that exon 8 has not been identified in cortical tau from humans, our study observed a statistical association between CNV mutations in exon 8 of the MAPT gene and cognitive decline." (PMID 40725212, 2025). "Another goal of the APPNL-G-F/MAPTP301S double transgenic mice is to recapitulate the development of MAPT pathology associated with cognitive decline in AD patients." (PMID 37292629, 2023). "The CamPaIGN study was the first to report an association between the MAPT H1/H1 genotype and cognitive decline in PD." (PMID 33613437, 2021). "We compared cognitive profiles cross-sectional in patients with bvFTD due to mutations in GRN, MAPT or C9orf72 and report patterns of cognitive decline in a subset of patients with follow-up data." (PMID 32052166, 2020). "Our findings suggest that early GMV loss in MAPT H1H1 PD patients increases their risk to develop cognitive decline." (PMID 29899731, 2018). "Notably, there appeared to be a discrepant trend in MAPT variant carriers for cognitive outcomes only, such that symptomatic males exhibited faster rates of cognitive decline than females, despite showing similarly attenuated rates of functional decline." (PMID 40277077, 2025). "Certain variants influence clinical trajectories differently: alleles in the GBA gene (e.g., p.E326K, p.N370S, and p.T369M) correlate with varying rates of motor and cognitive decline, whereas variants in MAPT and SNCA are associated with disparities in motor progression and disease severity." (PMID 41497575, 2025). "In addition, MAPT mutation carriers are known for their rapid cognitive decline once they become symptomatic, probably causing lower performance on neuropsychological tests compared to patients with a GRN or C9orf72 mutation in their early symptomatic stages." (PMID 39229325, 2024). "In addition, the MAPT H2 haplotype was associated with a higher rate of cognitive decline in an HD cohort." (PMID 35478426, 2022). "To disentangle heterogeneity in neurocognitive functioning, we also studied whether α-synuclein (SNCA) and microtubule-associated protein tau (MAPT) variants alter internetwork connectivity and/or accelerate cognitive decline." (PMID 35418853, 2022). "We further examined whether microtubule-associated protein tau (MAPT) risk variants, which may accelerate cognitive decline, altered the strength of regional functional connections." (PMID 34616286, 2021). "To unravel heterogeneity in the pathophysiological underpinnings of semantic cognition in PD, we examined whether MAPT risk variants, which are thought to accelerate cognitive decline early in PD, altered the strength of regional functional connections." (PMID 34616286, 2021). "We examined whether variations in apolipoprotein E (ApoE) and microtubule-associated protein tau (MAPT) genotypes are associated with cognitive decline in PD." (PMID 30155299, 2018). "Here we investigated whether an early reduction in cerebral GMV could be a mechanism by which PD patients with MAPT H1 homozygozis have an increased risk to develop cognitive decline." (PMID 29899731, 2018). "To conclude, the present work reports a set of structural brain changes associated with MAPT H1 homozygosis in PD which may increase the risk of developing cognitive decline in this population." (PMID 29899731, 2018). "The discrepancy may reflect the nature of the cohorts assessed, with negative associations in prevalent cohorts with longer disease durations, suggesting that the predominant effect of the MAPT H1 variant may be to accelerate cognitive decline within the early years of the disease." (PMID 27242557, 2016). "A previous ASO therapy targeting the MAPT gene (BIIB080) demonstrated that reductions in CSF p-tau181 levels correlated with a slowing of cognitive decline." (PMID 40588759, 2025).
cognitive decline (continued). "These cases include individuals with varying clinical characteristics, such as advanced disease stages in PSP cases, older age or cognitive decline in AD cases, and pathogenic mutations (e.g., TBK1, MAPT) in FTD cases." (PMID 39976789, 2025). "Specifically, polymorphisms affecting the MAPT, COMT, GBA, and APOE genotypes have been linked to cognitive decline." (PMID 37885554, 2023). "Variation in the MAPT gene has also been previously shown to predict cognitive decline in Huntington’s disease, such that H1 homozygotes had a slower decline in cognitive function compared with H2 carriers." (PMID 36519153, 2022). "Aside from APOE, common variants in MAPT,1,41–43COMT,24,42BDNE, MTHER, and SORL144 have been reported to influence cognitive decline (reviewed in Fagan and Pihlstrom45)." (PMID 33111402, 2021). "Converters with a MAPT and GRN mutation had mutual as well as gene-specific profiles of cognitive decline." (PMID 29627938, 2018). "In terms of cognitive progression, we found that 58% of patients with MAPT H1 homozygosis developed cognitive decline over a 4-year follow-up period." (PMID 29899731, 2018). "Our results suggest that in PD, harboring the MAPT H1H1 genotype is associated with an early decrease in GMV, even in cognitively preserved patients, possibly making this population more prone to cognitive decline." (PMID 29899731, 2018). "The similar patterns of cognitive decline in bvFTD as MAPT, and nfvPPA as GRN are related to the dominant genotype in each group (e.g. all nfvPPA converters have a GRN mutation)." (PMID 29627938, 2018). "Widespread neuronal overexpression of MAPT bearing the FTDP-17-linked P301L mutation in transgenic mice causes motor impairments, as well as cognitive decline and tau pathologies reminiscent of AD, but in the absence of Aβ accumulation." (PMID 23029293, 2012). "Other genes such as glucocerebrosidase (GBA), microtubule-associated protein tau (MAPT), and catechol O-methyltransferase (COMT), may also be associated with cognitive decline in PD." (PMID 38988604, 2024). "For this purpose, we analysed data from Track-HD, a multi-centre longitudinal study in Huntington’s disease gene carriers and focused on the role of intellectual enrichment (estimated at baseline) and the genes FAN1, MSH3, BDNF, COMT and MAPT in predicting cognitive decline and brain atrophy." (PMID 36519153, 2022). "• No MAPT mutations identified in GWAS studies. • Accelerated cognitive decline in H2 haplotype carriers." (PMID 33329322, 2020). "Consistently, our data also showed that KA induced cognitive decline in MAPT Tg mice." (PMID 31789603, 2019). "Cognitive decline in ScreeLing phonology (p = 0.046) and letter fluency (p = 0.046) were predictive for conversion to non-fluent variant PPA, and decline on categorical fluency (p = 0.025) for an underlying MAPT mutation." (PMID 29627938, 2018). "Thus the importance of our new findings lies in the unequivocal demonstration of tau pathology in the brains of patients with Huntington’s disease and the effect of MAPT H2 haplotype on cognitive decline in a large cohort of patients." (PMID 25953777, 2015). "Finally we investigated the relationship between MAPT haplotypes and the clinical progression of the disease, with a focus on cognitive decline, by performing a genotype–phenotype analysis in a large cohort of individuals with Huntington’s disease." (PMID 25953777, 2015). "Finally we highlight the clinical significance of this pathology by demonstrating that the MAPT haplotypes affect the rate of cognitive decline in a large cohort of patients with Huntington’s disease." (PMID 25953777, 2015). "On a genetic level, studies in clinically defined PD have suggested that genotypes at the MAPT and SNCA loci act synergistically to confer susceptibility to PD and that variation at MAPT may be particularly associated with cognitive decline." (PMID 22221882, 2012).
cognitive decline (continued). "Furthermore, spatial memory deficits and cognitive decline in AD could be ameliorated by FGF-2 through a simultaneous decrease in amyloid-β (Aβ) and microtubule-associated protein tau while increasing the number of resting ASTs in the hippocampal dentate gyrus." (PMID 37214403, 2023). "Hence, the disparity between studies may reflect the fact that these genetic variants have time-dependent effects on cognition which vary with disease stage: MAPT seems to have its greatest impact on cognitive decline in early PD, whereas APOE may have a more pronounced effect in later disease." (PMID 27242557, 2016). "Similarly, exploratory longitudinal descriptions provided valuable information on rate of cognitive decline with indeed rapid cognitive decline in GRN, but slow progression in C9orf72 and MAPT showing intermediate decline." (PMID 32052166, 2020). "We have shown that both APOE-ε4 and GBA mutations have an independent and additive effect on cognitive outcomes, adding to mounting evidence that these variants are key drivers of cognitive decline in PD, whilst common variants in SNCA and MAPT showed no significant impact." (PMID 35106798, 2022).
corticobasal degeneration (55 papers, 2010 to 2025). "The microtubule-associated protein tau (MAPT) H1 haplotype is the strongest genetic risk factor for corticobasal degeneration (CBD)." (PMID 33287913, 2020). "The aberrant aggregation of MAPT in neurons induced many irreversible, progressive neurodegeneration diseases, such as AD, corticobasal degeneration (CBD), and frontotemporal dementia with parkinsonism linked to chromosome 17 (FTDP-17)." (PMID 33192484, 2020). "Mice with a P301S mutation in the gene encoding tau (microtubule-associated protein tau; MAPT) that is associated with FTD and corticobasal degeneration (CBD) shows seizures." (PMID 40599392, 2025). "The most common primary tauopathies (where tau is the defining pathological feature) include progressive supranuclear palsy (PSP), corticobasal degeneration (CBD) and frontotemporal dementia linked to mutations in the MAPT gene that encodes tau." (PMID 33539581, 2021). "FTLD-tau encompasses genetic cases with tau inclusions due to mutations in microtubule-associated protein tau (MAPT) (FTLD-MAPT), but also sporadic cases including those with Pick bodies (FTLD-Picks), progressive supranuclear palsy (FTLD-PSP) or corticobasal degeneration (FTLD-CBD)." (PMID 32778130, 2020). "In addition to other variants, mutations in the MAPT gene that encodes Tau protein have been strongly linked with the pathogenesis of FTD, corticobasal degeneration (CBD), and other forms of dementia." (PMID 27809929, 2016). "Common genetic variation in the MAPT gene also contributes to sporadic forms of FTLD-Tau, including progressive supranuclear palsy (PSP) and corticobasal degeneration." (PMID 36845551, 2023).
Pick disease (51 papers, 2010 to 2026). A rare neurodegenerative disorder leading to dementia. "At first, neuronal and glial inclusions of hyperphosphorylated tau protein were identified in FTLD-tau, which represent nearly 30–40% of FTLD cases, and are found in patients carrying MAPT gene mutations, as well as in Pick’s disease, PSP, and corticobasal degeneration (CBD)." (PMID 26388768, 2015).
frontotemporal dementia with parkinsonism (38 papers, 2008 to 2025). "More than 50 mutations in the MAPT gene are currently known to be the causative factor in a proportion of patients affected by a condition formerly known as frontotemporal dementia and parkinsonism linked to chromosome 17 (FTDP-17)." (PMID 38592608, 2024). "Mutations in the microtubule-associated protein tau (MAPT) gene are responsible for frontotemporal dementia with parkinsonism linked to chromosome 17 (FTDP-17), a hereditary neurodegenerative tauopathy." (PMID 39060263, 2024). "Mutations in the gene (MAPT) encoding the tau protein that cause frontotemporal dementia with parkinsonism linked to chromosome 17 (FTDP-17 MAPT) demonstrate that alterations in tau are sufficient to cause neurodegeneration." (PMID 35229269, 2022). "SMaRT can correct splicing defects due to pathogenic MAPT mutations causing frontotemporal dementia with parkinsonism linked to chromosome 17 (FTDP-17)." (PMID 35067193, 2022). "Mutations in the tau gene (MAPT) are known to co-segregate with the disease of frontotemporal dementia with parkinsonism linked to chromosome 17 (FTDP-17)." (PMID 32255788, 2020). "Clinical symptoms in patients with MAPT mutations are generally heterogeneous and designated as frontotemporal dementia with Parkinsonism linked to chromosome 17 (FTDP-17MAPT)." (PMID 29370822, 2018). "Mutations in the microtubule-associated protein tau gene (MAPT) cause frontotemporal dementia and parkinsonism linked to chromosome 17 (FTDP-17T)." (PMID 24292008, 2014). "In this paper, mutations of MAPT cause frontotemporal dementia with parkinsonism linked to chromosome 17 (FTDP-17)." (PMID 22623900, 2012). "Familial forms of FTLD expressing prominent parkinsonian features have been linked to mutations in MAPT, formerly frontotemporal dementia and Parkinsonism linked to chromosome 17 (FTDP-17)." (PMID 21569259, 2011). "It should be noticed that an isolated presentation of semantic dementia in MAPT mutations is quite rare, and limited to sporadic case reports, and most commonly semantic deficits co-occur with a behavioral phenotype due to a common tropism of MAPT mutations." (PMID 38592608, 2024). "The discovery that microtubule-associated protein tau (MAPT) gene mutations caused frontotemporal dementia with parkinsonism linked to chromosome 17 (FTLD-17) was a historic moment, providing genetic evidence of dysfunction within tau alone as sufficient cause of neurodegeneration independent of Aβ." (PMID 37445986, 2023). "Indeed, until a few decades ago parkinsonian symptoms were regarded as a rare manifestation of FTLD associated with MAPT mutation, so the term frontotemporal dementia and parkinsonism linked to chromosome 17 (FTDP-17) was coined." (PMID 34943897, 2021). "In addition, several mutations in the MAPT gene have been identified in the inherited frontotemporal dementia and parkinsonism linked to chromosome 17 (FTDP-MAPT)." (PMID 34722523, 2021). "The 10+16 intronic mutation in MAPT gene, encoding tau, causes frontotemporal dementia and parkinsonism linked to chromosome 17 (FTDP-17), by altering the splicing of the gene and inducing an increase in the production of 4R tau isoforms, which are more prone to aggregation." (PMID 28319892, 2017). "Frontotemporal Dementia with Parkinsonism Linked to Chromosome 17 (FTDP-17) is a hereditary neurodegenerative disorder caused by mutations in the MAPT gene." (PMID 40423231, 2025). "Another gene, microtubule associated protein tau (MAPT), has been genetically linked to a dominant form of frontotemporal dementia and parkinsonism linked to chromosome 17 (FTDP-17) and genome-wide association studies report a strong association between MAPT and sporadic PD." (PMID 25426138, 2014).
breast carcinoma (34 papers, 2010 to 2025). "Subsequent survival analysis showed that high expression of GRSF1 predicted poor prognosis, whereas MAPT was associated with favorable survival outcomes in TCGA breast cancer patients." (PMID 34406386, 2021). "MAPT hypermethylation is a marker for lower five-year survival indicating that, similarly to breast cancer, low TAU expression is linked to a worse prognostic in both cancers." (PMID 33207722, 2020). "For example, high MAPT protein expression level has been linked to good prognosis in breast cancer, but to poor prognosis in ovarian cancer." (PMID 30823906, 2019). "The microtubule associated-protein tau has been identified as an effective positive prognostic indicator in breast cancer." (PMID 27447563, 2016). "We recently reported the preclinical immunotherapeutic potential of microtubule associated protein tau (MAP) against a variety of cancer types including breast carcinoma and Hodgkin's lymphoma." (PMID 27564103, 2016). "Gene expression levels of the microtubule associated protein tau have recently been described as inversely correlated with response to epothilones in breast cancer patients." (PMID 20098694, 2010). "Several of these genes have been linked to breast cancer (MAPT, HMGCS2, NR2F2, TFAP2B, NTN4, SEC14L2 and LTF)." (PMID 21209903, 2010). "In addition, we discovered six genes: CCNE1, CEP55, EGFR, EXO1, FGFR4, and MAPT associated with both types of breast cancer." (PMID 32724790, 2020). "A positive correlation between MAPT mRNA levels and survival was also reported in other cancers such as low-grade glioma, breast cancer, kidney clear cell carcinoma, lung adenocarcinoma, and pheochromocytoma/paraganglioma." (PMID 40319030, 2025). "The article explains that the possible reason is that the change of MAPT expression affects the sensitivity of breast cancer cells to chemotherapeutic drugs, which also has a certain guiding significance for our research." (PMID 38494472, 2024). "MAPT.AS1 transcribed from the antisense strand of the Microtubule Associated Protein Tau (MAPT) promoter region, exhibiting conflicting roles in breast cancer." (PMID 38326441, 2024). "We found a positive correlation between MAPT expression and survival in breast cancer, in line with previous studies." (PMID 37730697, 2023). "In that study, a positive correlation between MAPT expression and survival in glioma, breast cancer, kidney clear cell carcinoma, lung adenocarcinoma, and pheochromocytoma/paraganglioma was described." (PMID 37730697, 2023). "Here, we used dimethyl sulfate probing read out by mutational profiling (DMS-MaP) to assess MAPT pre-mRNA and mature mRNA structures in T47D cells, a breast cancer line, and in neuronal SH-SY5Y cells." (PMID 35695373, 2022). "Breast cancer cell lines and tissue samples confirmed the downregulation of MAPT in tamoxifen-resistant patients compared to the sensitive ones." (PMID 36499709, 2022). "Recent studies have suggested that elevated expression of MAPT predicts better survival outcomes in pediatric neuroblastoma, breast cancer, renal clear cell cancer, and low-grade glioma, which is consistent with the results of the present study." (PMID 34406386, 2021). "For example, MAPT is the most differentially expressed gene as a function of response to preoperative Paclitaxel treatment in breast cancer, whereby low TAU mRNA predicted complete response to taxanes, as confirmed also in additional studies." (PMID 33207722, 2020).